BAP1 (BRCA1 associated deubiquitinase 1)
Diseases named in the same sentence as BAP1 in open-access papers (continued):
Sharing a sentence is not in itself a finding about the gene and the disease.
cancer (continued). "Notably, the tumor suppressor BRCA1-associated protein 1 (BAP1) is involved in apoptosis and ferroptosis in different cancer cells." (PMID 35205167, 2022). "Together with our findings, these studies raise the intriguing possibility that BAP1 loss could play a more general role in centrosome amplification in cancer, which will merit future investigations." (PMID 35474453, 2022). "Mutations in BAP1 may affect the deubiquitinase activity of BAP1 protein or lead to deletion of its nuclear localization sequence, disrupting its anti-cancer function and ultimately causing tumorigenesis." (PMID 36003792, 2022). "However, it should be noted that there are other non-BAP1 mutations associated with cancer predisposition in high-risk cancer families with MM." (PMID 36012262, 2022). "In addition, Shahriyari L and collaborators described the existence of a correlation between the expression of USP19, RBM15B and the tumor suppressor gene BAP1 (BRCA1 associated protein-1) in different type of cancers." (PMID 35646888, 2022). "Cancer-associated BAP1 mutations also result in impaired cellular senescence." (PMID 36068610, 2022). "Additionally, BAP1 deficiency in cancer cells is associated with SLC7A11 upregulation and ferroptosis resistance." (PMID 35280777, 2022). "Furthermore, sporadic ccRCC shows mutations to BAP1 in ~15% of cases and loss of BAP1 in the somatic setting are associated with lower overall and cancer-specific survival." (PMID 36421797, 2022). "In view of BAP1 immunomodulatory functions, BAP1 alterations could prove useful as possible biomarkers of response to immunotherapy in patients with BAP1-associated cancers." (PMID 35381901, 2022). "Two of the individual CTCs (CTC1 and CTC2) and the CTC pool had homogenous copy-number profiles, and included amplification on 1q and 8q (MYC), 11q (CCND1, FGF3, FGF4) and allelic loss of regions including several cancer genes on 3p (BAP1), 13q(RB1, BRCA2) and 17p (MAP2K4)." (PMID 36088510, 2022). "Survival analysis on 1,207 patients with prognostic and mutation data was conducted to investigate whether the functional status of the BAP1 was associated with the survival outcome of cancer patients." (PMID 35918352, 2022). "Interestingly, in several families, there are individuals carrying mutated BAP1 who harbor more than one type of primary cancer, and this observation strongly suggests that multiple tissue lineages are affected by BAP1 deficiency." (PMID 33802313, 2021). "Indeed, germline mutations in BAP1 have been shown to be associated with an increased risk of developing MPM as well as other types of cancer, primarily melanoma." (PMID 34199544, 2021). "The expression of BAP1, with mutations associated with human cancers, cannot promote ferroptosis." (PMID 33919439, 2021). "However, we clearly demonstrate the presence of subclonal NF2 mutations in three patients, characterized by clonal mutation in other key MPM mutated cancer genes including BAP1, SETD2, and the TERT promoter." (PMID 34261524, 2021). "The impact of a heterozygous RECQL4 mutation on cancer predisposition unknown, particularly in the context of simultaneously inherited DNA damage and repair gene mutations like BAP1 and/or MSH6." (PMID 33541411, 2021). "BAP1 is another tumor suppressor that is frequently mutated or deleted in several human cancers." (PMID 33000412, 2021). "Indeed, BAP1+/− mice carried bi-allelic inactivation of the BAP1 gene coherently to its predisposing role as a cancer susceptibility candidate gene." (PMID 33802313, 2021). "However, contradicting these findings, reducedexpression of the BRCA1-associated protein 1 (BAP1) increases theincidence of cancer in parallel to a reduction of IP3Ractivity (Bononiet al., 2017)." (PMID 37366382, 2021).
cancer (continued). "Several associations of significant HRD-predisposing genes and cancer types in specific populations were previously reported for the same population, for example, BAP1 with BRCA in the ‘White’ and ‘African American/Black’ populations and ATM with STAD in the ‘White’ and ‘Asian’ populations." (PMID 34945758, 2021). "Cancer-derived mutations are enriched in functionally important regions of BAP1—within the catalytic domain of BAP1, disrupting the catalytic triad or structural integrity of the domain; and within the ubiquitin binding site or crossover loop, disrupting the binding interface between BAP1 and ASXL1." (PMID 33105797, 2020). "Interestingly, a cancer mutation consisting of a small in-frame deletion in the CTD domain of BAP1 results in its selective dissociation from ASXLs and inability to deubiquitinate H2Aub and regulate cell proliferation." (PMID 33230107, 2020). "Furthermore, mutations in specific genes have been associated to the development of MPM, such as germline mutations/inactivations discovered in the tumor suppressor gene BRCA1-associated protein 1 (BAP1) in cases with a family history of cancer." (PMID 33537296, 2020). "Promising targets for potentially interesting inhibitors are the proteins of the JAK/STAT, Wnt/β-catenin, Hedgehog and Notch signalling pathways, inhibitors that target mutations in chromatin-remodelling genes, such as ARID1A, PBRM1, and BAP1, and inhibitors of cancer-associated fibroblasts." (PMID 32423017, 2020). "Furthermore, the pro-apoptotic function of another tumor suppressor gene BAP1 that is mostly deleted or mutated in various human cancer types, is facilitated by attachment to 14-3-3 protein." (PMID 32742605, 2020). "Thus, in cancer cells with MLL3 or BAP1 mutations, reduction of H3K27me3 via EZH2 inhibitors can restore the balance of H3K27me3 at enhancers where UTX is not properly recruited." (PMID 31221981, 2019). "However, the addition of PBRM1 mutation to BAP1 mutation, which did correlate with a poor prognosis, increased the risk of cancer death (HR 4.18)." (PMID 31861590, 2019). "The BAP1 (BRCA1-associated protein 1) gene is associated with a variety of human cancers." (PMID 31635116, 2019). "In addition, the tumor suppressor breast cancer 1 gene (BRCA1) associated protein-1 (BAP1), a deubiquitinase that is commonly silenced or lost in many cancers, also represses xCT expression." (PMID 31100816, 2019). "In addition, to determine the diagnostic capacity of the BAP1 gene for control and cancer samples, we used the area under the receiver operating characteristic curve (AUC)." (PMID 31635116, 2019). "Importantly, a cancer-associated mutation of BAP1 in its CTD, BAP1ΔR666-H669, that abrogates its interaction with ASXL1 and ASXL233, also failed in promoting DEUBAD monoubiquitination." (PMID 30349006, 2018). "Notably there have been no trials of any death receptor agonists in MM or indeed any cancer with a high proportion of BAP1 mutations." (PMID 29345617, 2018). "ASXL1 and ASXL2, frequently mutated in cancer, facilitate BAP1 DUB activity." (PMID 30455474, 2018). "Detecting BAP1 mutations in appropriate cancer patients is important since management may be affected." (PMID 30001711, 2018). "Thus, mutations in BAP1, along with family history, can be used as an assessment for a patient’s risk of certain cancers, and confers importance to the knowledge of a patient’s BAP1 mutation status." (PMID 29166932, 2017). "Thus, mutation of BAP1, either somatically or in the germline, is associated with a range of cancers, and the biological effects of BAP1 loss are likely to manifest through a range of downstream pathways." (PMID 28062663, 2017). "In addition, future studies should be integrated with genomics data to assess the effects of mutations of genes commonly mutated in ccRCC (e.g. VHL, SETD2, BAP1) on the cancer kinome." (PMID 28418903, 2017).
cancer (continued). "Interestingly, S10, E31, Y33, R227, and L230 residues of BAP1 were found to be mutated in many cancers as specified in the COSMIC database." (PMID 28935764, 2017). "In addition its clear role in ubiquitination and maintaining protein balance, BAP1 has been shown to be critical for a range of cellular processes associated with cancer, including differentiation and DNA repair." (PMID 29166932, 2017). "We hypothesized that common, germline genetic variants in BAP1 may also contribute to the risk of developing different types of cancer." (PMID 29088836, 2017). "Cancer cellfractions were higher for the broad or arm-level loss of chromosome 3 than forBAP1 mutations, followed by PBRM1mutations, suggesting that these events occur chronologically (3p loss,BAP1, PBRM1) in CCA development." (PMID 28297679, 2017). "Besides the well-known MPM-associated genes, CDKN2A, NF2 and BAP1, other interesting cancer-associated genes were listed as frequently involved in a copy number loss (e.g. EP300, SETD2 and PBRM1)." (PMID 29371938, 2017). "In this study, we performed an extensive investigation in different types of cancer that included nearly 10,000 cancer cases and 5,000 healthy controls to determine the association of the common germline genetic variants in BAP1 with the risk of developing different types of cancer." (PMID 29088836, 2017). "SETD2, PTEN, RNF43, HRAS, EPHA2, and BAP1 were also linked to primarily positive associations in more than one cancer type, suggesting that they may play a general role in CGI hypermethylation." (PMID 29125844, 2017). "Carriers of heterozygous germline BAP1 mutations (BAP1+/−) develop cancer." (PMID 28665402, 2017). "The specific type of cancer that develops in BAP1 mutation carriers might depend on additional modifier genes." (PMID 28229253, 2017). "It is possible that some variants that were not identified as loss-of-function alleles by functional testing (deubiquitinase assays), may still impair BAP1 function and predispose to cancer types associated with the BAP1 syndrome phenotype." (PMID 28062663, 2017). "In the present report, we have demonstrated for the first time that cancer associated catalytic domain mutants (I47F, F81V, A95D and G178V) of BAP1 show a loss of enzymatic activity, significantly decreased protein stability and subsequently lead to beta amyloid aggregation in vitro." (PMID 26680512, 2015). "BAP1 mutations usually cause cancer after the peak of the reproductive age is passed." (PMID 26683624, 2015). "Therefore, activation of this response due to conformational change in BAP1 links mutational effect of BAP1 with cancer." (PMID 26680512, 2015). "We and others identified germline mutations in the BRCA-associated protein 1 (BAP1) gene, predisposing for a novel cancer syndrome linked to an inherited very high risk of developing mesothelioma, uveal melanoma, and possibly additional cancers." (PMID 28548074, 2014). "Defective HR and increased sensitivity to radiation due to BAP1 deficiency may, therefore, lead to genomic instability, a hallmark of cancer." (PMID 25593912, 2014). "In addition, germline BAP1 mutations haverecently been identified, conferring susceptibility to the development of MM and othertypes of cancer." (PMID 25210967, 2014). "MBAITs provide physicians with a marker to identify individuals who may carry germline BAP1 mutations and thus are at high risk of developing associated cancers." (PMID 22935333, 2012). "We then conducted a meta-analysis of all the studies reporting BAP1-mutated families to survey cancer risk related to the germline BAP1 mutation (means were compared using t-test and proportions were compared with Pearson χ2 test or two-tailed Fisher’s exact test)." (PMID 22935333, 2012).
cancer (continued). "Furthermore, even if there is this increased incidence, it is still unclear whether the BAP1 germline mutation is a direct cause, or whether it may be another association with cancer or its treatment." (PMID 38824259, 2024). "However, these cancer types occur also sporadically in patients who carry somatic BAP1 mutations." (PMID 38785832, 2024). "Indeed, CRISPR/Cas9 screens show BAP1 is an essential/fitness gene, suggesting cancers may need to reprogram essential pathways to tolerate BAP1 loss of function." (PMID 36669126, 2023). "Thus, we have established a model to study BAP1 cancer-related mutations in C. elegans, and our data points toward vulnerabilities that should be studied to explore therapeutic opportunities within the complexity of BAP1 tumors." (PMID 36980270, 2023). "Therefore, genome instability caused by inactivating BAP1 mutations may play a key driving role in the tumorigenesis of human cancers associated with BAP1 cancer syndrome." (PMID 37009801, 2023). "Hence, BAP1 inactivation emerged as directly linked to the tumorigenesis process of these cancers." (PMID 36318367, 2022). "Despite the evidence that BAP1 enforces control of the epigenetic landscape and influences genomic integrity, it is still unclear whether the intersection of these two processes underlies a role of BAP1 in cancer." (PMID 36318367, 2022). "Additional results from the METABRIC datasets showed that ORN could characterize critical mechanisms of cancer and connect them to less studied somatic mutations (e.g., BAP1, MIR604, MICAL3, and telomere activities), which may generate novel hypothesis for targeted therapy." (PMID 33819263, 2021). "Moreover, cancer-associated BAP1 mutants lose its inhibition of SLC7A11 and repress ferroptosis." (PMID 33294126, 2020). "Furthermore, we evaluated how patient age, sex, and race may be associated with BAP1 gene expression and patient survival with these cancers." (PMID 30716094, 2019). "However, the role of common germline genetic variants in BAP1 on the risk of developing different types of cancer is largely unknown." (PMID 29088836, 2017). "In summary, our data indicate that the Warburg effect, in addition to being a hallmark of cancer cells, is also found in normal cells from individuals carrying heterozygous germline BAP1 mutations and may contribute to the high incidence of cancer observed among them." (PMID 28665402, 2017). "Although these previous studies have provided the functional characterization of BAP1 and identified rare mutations in several cancers, the role of common germline genetic variants in BAP1 on the risk of developing different types of cancer remains largely unknown." (PMID 29088836, 2017). "BAP1 loss might also be associated with cancer progression and metastasis." (PMID 25970771, 2015). "Thus BAP1 aggregation could be one of the causes for cytoplasmic sequestration or perinuclear accumulation for cancer associated mutants." (PMID 26680512, 2015). "Interestingly, half (7/14) of the known germline mutations to date localized to the C-terminus of BAP1 (close to BRCA1 binding region) suggesting that this may represent the critical domain for heritable cancer risk." (PMID 22545102, 2012). "Germline pathogenic variants in BAP1 are associated with BAP1 tumor predisposition syndrome (BAP1-TPDS), and an increased risk for different cancers and preneoplastic lesions." (PMID 41843333, 2026). "Alternatively, many studies on BAP1 or SETD2 have been conducted in other cancers and need to be confirmed in ccRCC." (PMID 41602827, 2026). "Exploring the PanCancer data, we found that BAP1 gene expression was inconsistently expressed in 22 cancers." (PMID 40136571, 2025).
cancer (continued). "We now provide a rationale for stratifying patients with BAP1-mutant cancers for treatment with SRC inhibitors and autophagy inducers." (PMID 40754831, 2025). "To gain a deeper understanding of the expression patterns of BAP1 in PDAC and its implications for prognosis, we conducted a comparative analysis of BAP1 expression in cancer tissues versus adjacent tissues within our internal cohort." (PMID 40083694, 2025). "We describe that BAP1 loss increases the mRNA expression and activation of the proto-oncogene SRC in several cancers, suggesting that BAP1 is a transcriptional repressor of SRC." (PMID 40754831, 2025). "Understanding BAP1’s role in the metabolic processes of cancer cells is crucial for predicting treatment efficacy." (PMID 40506895, 2025). "The chromatin remodeling activity of BAP1 directly represses SLC7A11 transcription by removing H2AK119ub1, making BAP1‐mutant cancers hypersensitive to GPX4 inhibitors." (PMID 40919133, 2025). "A reduction of MHC-II cluster genes was observed in all BAP1-depleted cell lines from 3 different cancer types." (PMID 39817454, 2025). "BAP1 has been known as a common essential factor, the depletion of which leads to cell death and apoptosis in many cell types, including both normal and cancer cells." (PMID 39817454, 2025). "Six of these genes are established genes for one or more of the cancers, the exception being BAP1, which had a posterior probability of 0.824 in the breast-prostate model." (PMID 40073867, 2025). "These phenotypes are similar to those reported due to loss of function of other chromatin regulators and validate the allele calyHMC04109 as a tool in future mechanistic studies to understand the role of BAP1 in disease and cancer." (PMID 41022584, 2025). "Loss-of-function BAP1 mutations sensitize cancer cells to PARP inhibitors (PARPi), similar to BRCA-mutated cancers." (PMID 41226789, 2025). "SLC7A11, the cystine transporter protein, was identified as a critical BAP1 target gene in human cancers." (PMID 38267442, 2024). "Here, we describe the prevalence and characteristics of splenic lesions in individuals with BAP1-TPDS followed at a comprehensive cancer center." (PMID 38824259, 2024). "Together, our expanded BAP1 mutant samples revealed a transcriptional signature in cancer cells, supporting BAP1's influences on cellular plasticity and cell identity maintenance." (PMID 38045292, 2024). "However, the mechanisms by which BAP1 loss or mutations regulate cancer immunity remain unclear." (PMID 39350280, 2024). "In particular, the SFR of the BAP1 gene promoter was statistically significantly higher in cancer patients." (PMID 39000483, 2024). "These would be valuable to reveal underlying mechanisms by which mutations in BAP1 and SETD2 exert diverse effects on cancer progression in ccRCC." (PMID 38808948, 2024). "BRCA1-associated protein-1 (BAP1) is a member of the ubiquitin C-terminal hydrolase (UCH) subfamily of DUBs, the function of which in cancers is well studied." (PMID 38562929, 2024). "Although the binding of Med1 and BAP1 involved in the cancer growth or metastasis, mechanisms are still unclear." (PMID 38708315, 2024).